TERT (telomerase reverse transcriptase)
Diseases named in the same sentence as TERT in open-access papers (continued):
Sharing a sentence is not in itself a finding about the gene and the disease.
sarcoma (25 papers, 2014 to 2025). A usually aggressive malignant neoplasm of the soft tissue or bone. "Although TERT promoter hotspot mutations are uncommon across all sarcomas, they occur relatively often in myxoid liposarcoma (74% of cases) but are rare in UPS." (PMID 41293148, 2025). "Mutations in the TERT promoter were found in seven distinct sarcoma subtypes, with an overall incidence of 9.5%87." (PMID 39239547, 2024). "Previous studies examined the relationship between telomere length and TERT promoter mutations in the MLS sarcoma subtype." (PMID 39239547, 2024). "Paired analysis of macrodissected WDCS and the high-grade sarcoma components from 7 patients with DDCS revealed TERT promoter mutations as common, early events." (PMID 36926116, 2023). "Due to the variety of sarcoma subtypes, the prevalence of TERT promoter mutations varies widely, and the highest TERT promoter mutation rate is reported in myxoid liposarcoma (79.1%)." (PMID 36979671, 2023). "We observed TERT promoter mutations at an overall frequency of 9.5% distributed over 7 different sarcoma subtypes." (PMID 29463038, 2018). "In the literature, only a few studies exist on telomeres or TERT promoter mutation status in sarcoma." (PMID 29463038, 2018). "We determined the prevalence of TERT promoter mutations in soft tissue sarcomas of 341 patients comprising 16 entities and in 16 sarcoma cell lines covering 7 different soft tissue sarcoma types." (PMID 24726063, 2014). "Within the collection of sarcoma cell lines examined, TERT promoter mutations were detected in two MLS and in one of three MPNST cell lines." (PMID 24726063, 2014). "TERT promoter mutations are frequent in MLSs including their round cell variants, representing the most prevalent mutation identified in this sarcoma entity to date, and in a minor fraction of SFTs, MPNSTs and SSs." (PMID 24726063, 2014). "In the remaining cases, TERT promoter mutations were found only in 7/302 sarcoma samples and confined to SFTs (4/31; 13%), MPNSTs (2/35; 6%), and SSs (1/25; 4%)." (PMID 24726063, 2014). "The aim of our study was first to investigate the prevalence of TERT promoter mutations in the different sarcoma subtypes and second to analyze the relation between presence of TERT promoter mutations and telomere lengths in a specific subtype of sarcomas, the MLSs." (PMID 29463038, 2018). "We next focused on whether the presence of TERT promoter mutations correlated with clinical features of our sarcoma cohorts." (PMID 29463038, 2018). "Therefore, the present study was conducted to investigate the prevalence of TERT promoter mutations in a comprehensive series of 341 soft tissue tumors comprised of 16 types including rare entities and in 16 cell lines of seven sarcoma types." (PMID 24726063, 2014). "The majority of sarcomas are devoid of TERT promoter hotspot mutations." (PMID 24726063, 2014). "We also sequenced 16 sarcoma cell lines for the TERT promoter hotspot mutations." (PMID 24726063, 2014). "TERT promoter mutations were detected in 36 of 341 sarcoma samples from 341 patients (10.5%)." (PMID 24726063, 2014). "In addition, paired analysis of macrodissected WDCS and the high-grade sarcoma components revealed TERT promoter mutations as common, early events in both components, but acquisition of additional copy-number gains and losses in the high-grade sarcoma component not seen in the WDCS component." (PMID 36926116, 2023). "Despite the overall low prevalence in this tumor group, TERT promoter mutations revealed to be a highly recurrent event in MLS and currently represent the most prevalent mutation identified in this sarcoma entity (74%)." (PMID 24726063, 2014). "The fourth gene deregulated in TFCP2-rearranged sarcoma, besides ALK, CDKN2A, and MTAP, is TERT, encoding the catalytic component of the telomerase complex that protects dividing cells from progressive telomere shortening, subsequent senescence, and malignant transformation." (PMID 38168093, 2024).
sarcoma (continued). "Specifically, TFCP2-rearranged sarcoma expressed a TERT variant lacking exons 1 and 2 (Δex1-2), and intronic RNAs were transcribed in the reverse direction, starting exactly at the TFCP2 binding region." (PMID 38168093, 2024). "The percentage of TERT promoter mutation is low in sarcomas except for myxoid liposarcoma because 20 to 65% of sarcoma activates ALT but not telomerase to elongate telomeres." (PMID 30709063, 2019). "Furthermore, intratumoral heterogeneity of TERT expression and telomerase activity has been observed in sarcomas, in particular in liposarcomas." (PMID 24726063, 2014). "Taken together, TFCP2-rearranged sarcoma likely represents a separate entity characterized by distinct transcriptional and DNA methylation profiles, an unusual degree of genomic instability, truncated ALK variants, ALK and TERT overexpression, and recurrent CDKN2A/MTAP co-deletions." (PMID 38168093, 2024). "Genes located in 5p that have been suggested as possible amplicon targets in sarcomas include NKD2, TERT, IRX2, TRIO, AMACR, SKP2 and RICTOR." (PMID 28652867, 2017). "C-circles, TERT expression, high telomere content with heterogenous telomere length, and APBs have been used to screen sample sets to establish ALT frequencies amongst sarcomas; however, each of these techniques have their own advantages and disadvantages." (PMID 39224814, 2024). "Because UPS and liposarcoma also harbor TERT alterations in a largely non-overlapping pattern, these sarcomas may acquire the ability to aberrantly maintain telomeres through multiple independent mechanisms." (PMID 35705560, 2022). "Finally, comparing TERT isoform expression with relative telomere length, a surprising significant negative correlation between FL-TERT expression in sarcomas was found." (PMID 33924498, 2021). "Finally, we discovered a recurrent fusion in sarcoma encoding the non-catalytic portion of TRIO kinase, which resulted in the upregulation of the transcription of telomerase reverse transcriptase (TERT) in those tumours." (PMID 25204415, 2014).
skin cancer (25 papers, 2013 to 2025). "Molecular analysis revealed EZH1 mutations in both the Out‐N and STc of TFND, while KRAS and TERT promoter mutations were restricted to STc and the skin tumor." (PMID 41090246, 2025). "Of the two main TERT promoter mutations, −124 C > T and −146 C > T, the former, with the exception of skin neoplasms, is overwhelmingly predominant in most cancers." (PMID 32409749, 2020). "When testing significance of affinity changes against the skin cancer specific mutation signature model and a uniform model, the same significantly affected TFs were found in the TERT block, with small differences in the ranking." (PMID 31001324, 2019). "It was previously reported that TERT transgenic mice were more susceptible to develop skin tumors upon chemical carcinogenesis compared with normal mice." (PMID 26971878, 2016). "To estimate the robustness of the choice for the upper limit of 10 potential regulators in our MIPRIP analysis, we investigated models with other limits (1 up to 50 regulators) and tested them using the melanoma skin cancer samples with a TERT promoter mutation." (PMID 31888467, 2019). "We applied this to data of the melanoma skin cancer samples with TERT promoter mutation." (PMID 31888467, 2019). "The skin tumor resembled STc of the primary TFND and harbored EZH1, KRAS and TERT promoter mutations." (PMID 41090246, 2025). "The skin tumor was histologically identical to In‐N and exhibited mutations, including EZH1 Y642F, KRAS G60R, and TERT‐p C228T, which were also identified in In‐N." (PMID 41090246, 2025). "The KRAS G60R mutation was detected in In‐N (VAF 36.3%) and skin tumor (VAF 23.0%), while the TERT‐p C228T mutation was detected in In‐N (VAF 35.5%) and skin tumor (VAF 25.9%)." (PMID 41090246, 2025). "At the germline level, the association between 39 SNPs at telomere-related loci, including TERT, TRF1, TRF2, TNKS2, POT1, TERT-CLPTM1L and the risk of skin cancer was investigated in a nested case-control study including 285 Caucasian cSCC patients." (PMID 30884806, 2019). "Of note, emerging reports are showing that somatic, non–coding mutations within promoter regions of TERT and DPH3-OXNAD1 genes are common in all types of skin cancer, including BCC." (PMID 29165358, 2017). "Similarly, TERT promoter mutations, seen as key driver mutations in HCC, are present in multiple other cancers including bladder and skin cancer." (PMID 31608239, 2019). "While TERT promoter mutations are frequent in many cancers, we did not observe the DPH3 mutations in three non-skin cancers that were screened in this study." (PMID 26416425, 2015).
thyroid nodule (25 papers, 2016 to 2025). A small circumscribed mass in the THYROID GLAND that can be of neoplastic growth or non-neoplastic abnormality. "In 2014, Liu and Xing were the first to investigate the utility of TERT mutations in thyroid nodule FNAB." (PMID 34702207, 2021). "This study aimed to investigate the diagnostic utility of BRAF, NRAS, and TERT promoter mutation in thyroid nodules at Dharmais Cancer Hospital." (PMID 33247684, 2020). "The relationship could also be explained by the length of time the thyroid nodule had to develop, which could lead to a bigger size, a higher AF and a higher likelihood of a second genetic alteration, such as a TERT promoter mutation." (PMID 40940948, 2025). "Discrimination of interpatient variabilities in RAS in combination with BRAF V600E and TERT promoter variants could facilitate cytology examinations in preoperative precision malignancy diagnosis among patients with thyroid nodules." (PMID 38758552, 2024). "Thus, there is a compelling need for a diagnostic test to determine the existence of the TERT promoter mutations early in the identification of malignant thyroid nodules to inform management decisions that can affect clinical outcomes of these patients." (PMID 38441247, 2024). "This study supports the hypothesis that thyroid nodules positive for both TERT promoter mutations and other mutations are more likely to harbor aggressive features than thyroid nodules positive for TERT promoter mutations alone." (PMID 36672362, 2023). "Molecular markers, such as the BRAF V600E mutation or the TERT mutation, have been well studied in large cohorts, and the management of thyroid nodules harboring these mutations has also been recommended in the American and the European Thyroid Association Guidelines." (PMID 33923728, 2021). "With the analysis of genetic profiles in thyroid nodules, BRAF V600E, TERT mutations, and gene fusions were included in the 6-gene test panel." (PMID 40586006, 2025). "The results of the 6-gene test panel (BRAF V600E, TERT mutations, and gene fusions) demonstrated excellent diagnostic performance with high specificity and PPV in diagnosing thyroid nodules." (PMID 40586006, 2025). "The analytical robustness and reproducibility of the Afirma TERT test support its routine clinical use among thyroid nodules with indeterminate cytology that are Afirma Genomic Sequencing Classifier suspicious or among Bethesda V/VI nodules." (PMID 38441247, 2024). "The role of TERT promoter and BRAFV600E mutation analysis has also been demonstrated for the diagnostic and prognostic evaluation of thyroid nodules processed with liquid-based cytology." (PMID 37627081, 2023). "TERT positive patients had the largest thyroid nodules of 16.2 (1.9–27.2) mL, fusions 3.8 (0.3–22.2) mL, and BRAF positive 2.3 (0.3–12.2) mL." (PMID 35625691, 2022). "Molecular techniques such as TsV3 enhance the management of thyroid nodules by identifying mutations highly specific for malignancy such as BRAF V600E, RET or TERT, ultimately reducing the number of diagnostic thyroidectomies required." (PMID 36612045, 2022). "The mutant TERT promoter combined with other genetic biomarkers is required to improve the accuracy of thyroid nodules diagnosis." (PMID 36394204, 2022). "In an investigation of 308 thyroid nodules, eight nodules were positive for TERT, of which all demonstrated malignancy on surgical pathology." (PMID 34702207, 2021). "There is a paucity of research assessing the utility of BRAFV600E and TERT for profiling thyroid nodules using ddPCR techniques." (PMID 34702207, 2021).
thyroid nodule (continued). "The combined analysis of the mutant TERT promoter and other biomarkers is thus required to achieve a higher accuracy of thyroid nodule diagnosis." (PMID 27438857, 2016). "Therefore, the targets widely recognized and recommended by scholars at home and abroad were selected to compose a 6-gene test panel for thyroid nodule diagnosis, including BRAF V600E mutation, TERT mutation, and gene fusions (CCDC6-RET, NCOA4-RET, ETV6-NTRK3, EML4-NTRK3, STRN-ALK, and PAX8/PPARG)." (PMID 40586006, 2025). "Therefore, we reasoned that the combination of FNA with TERT promoter mutation analysis might be helpful to select the appropriate management and to predict clinical prognosis, particularly when thyroid nodules show non-parallel orientation by US." (PMID 29312581, 2017). "Pre-operative FNAB molecular testing of thyroid nodules by ddPCR has recently been validated for BRAFV600E and RAS mutations but did not include TERT." (PMID 34702207, 2021). "v2 (validated in the setting of FN/SFN cytologies), commercially available molecular panels for thyroid nodules found indeterminate on FNA do not include TERT promoter analysis." (PMID 29085338, 2017). "Nevertheless, TERT mRNA assessment could be very helpful for thyroid nodule diagnosis if there are no substantial lymphocyte infiltrations." (PMID 36394204, 2022).
anaplastic thyroid carcinomas (24 papers, 2014 to 2025). "In accordance with our findings, the TERT promoter mutation has been previously shown to correlate with larger nodule size in other carcinomas such as anaplastic thyroid carcinoma (ATC)." (PMID 40940948, 2025). "In poorly differentiated and anaplastic thyroid cancers, TERT promoter mutations are often clonal events, underscoring their role in driving tumor evolution toward more aggressive phenotypes." (PMID 40363930, 2025). "Two nodules with TERT mutation detected in our study were also associated with malignancy, which included anaplastic thyroid carcinoma and Hürthle cell carcinoma." (PMID 35247035, 2022). "Elevated TERT levels were significantly associated with arguably more disease including extrathyroidal extension and anaplastic thyroid cancer." (PMID 34702207, 2021). "Moreover, differentiated high-grade follicular cell-derived, poorly differentiated, and anaplastic thyroid carcinomas frequently harbor TERT promoter mutations." (PMID 36984536, 2023). "In particular, the presence of demethylation (expressed as the decrease of 5-hydroxymethylcytosine consequent to the downregulation of ten-eleven translocation family of 5-mC hydroxylases) has been associated with the presence of TERT promoter mutations and anaplastic thyroid cancer histology." (PMID 33543394, 2021). "TERT was positive in all four cases of anaplastic thyroid cancer." (PMID 34702207, 2021).
idiopathic pulmonary fibrosis (24 papers, 2009 to 2025). Idiopathic pulmonary fibrosis (IPF) is a nonneoplastic pulmonary disease that is characterized by the formation of scar tissue within the lungs in the absence of any known cause. "Apart from cancer, impairment in TERT may cause telomere shortening, resulting in age-related diseases such as idiopathic pulmonary fibrosis (IPF), dyskeratosis congenita and aplastic anemia." (PMID 28264499, 2017). "Heterozygous TERC and TERT mutations have also been implicated in cases of idiopathic pulmonary fibrosis (IPF), a chronic progressive lung disease with irreversible fibrosis leading to respiratory failure in most cases within 5 years." (PMID 19419704, 2009). "Sequence variants in genes for surfactant proteins (SFTPC, SFTPA1, SFTPA2, ABCA3), polymorphisms in MUC5B or TOLLIP, and mutations in telomere genes (TERT, TERC, PARN, and RTEL1) are associated with an increased risk of idiopathic pulmonary fibrosis (IPF)." (PMID 36864460, 2023). "Moreover, mutations in essential telomerase genes, telomerase reverse transcriptase (TERT) and RNA template (TR), are associated with idiopathic pulmonary fibrosis (IPF) and COPD." (PMID 29751799, 2018). "Genotyping of rs2736100 [C/A] in TERT and rs1278769 [G/A] in ATP11A was conducted in 98 RA patients with usual interstitial pneumonia, 120 with nonspecific interstitial pneumonia (NSIP), 227 with AD, and 422 without chronic lung disease using TaqMan assays." (PMID 38003027, 2023).